SEC23B (SEC23 homolog B, COPII component)
Diseases named in the same sentence as SEC23B in open-access papers:
SEC23B is named in the same sentence as 47 diseases in open-access papers, as found by Europe PMC text mining. Sharing a sentence is not in itself a finding about the gene and the disease. The quoted sentences say what the papers report.
Congenital dyserythropoietic anemia type II (19 papers, 2010 to 2025). Congenital dyserythropoietic anemia type II (CDA II) is the most common form of CDA (see this term) characterized by anemia, jaundice and splenomegaly and often leading to liver iron overload and gallstones. "In contrast, mutations in SEC23B result in congenital dyserythropoietic anemia type II (CDAII), an autosomal recessive disorder characterized by anemia and increased numbers of bi/multinucleated red blood cell precursors in the bone marrow." (PMID 36594468, 2023). "A previous study demonstrated that a SEC23B mutation causes congenital dyserythropoietic anemia type-II (CDAII) 4, while the SEC23A mutation causes cranio-lenticulo-sutural dysplasia (CLSD) due to abnormal endoplasmic-reticulum-to-Golgi trafficking." (PMID 31595159, 2019). "In humans, loss of function mutations in SEC23B result in Congenital Dyserythropoietic Anemia type II (CDAII), a disease limited to defective erythroid development." (PMID 27297878, 2016). "SEC23B deficiency in humans results in the unique red cell disorder congenital dyserythropoietic anemia type II (CDAII)." (PMID 39545422, 2024). "Congenital dyserythropoietic anemia type II (CDAII) results from loss-of-function mutations in SEC23B." (PMID 34818036, 2021). "In related Cases 25–26, autopsies identified hepatomegaly and erythroblastosis, supporting a diagnosis of SEC23B-related congenital dyserythropoietic anemia type II in both pregnancies." (PMID 41595457, 2025). "Previous research has demonstrated that SEC23B mutations may cause congenital dyserythropoietic anemia type II (CDAII), while the mutations of SEC23A may cause cranio-lenticulo-sutural dysplasia (CLSD)." (PMID 37046730, 2023). "Biallelic pathogenic variants in the SEC23B gene cause congenital dyserythropoietic anemia type II (CDA II), a rare hereditary disorder hallmarked by ineffective erythropoiesis, hemolysis, erythroblast morphological abnormalities, and hypo-glycosylation of some red blood cell membrane proteins." (PMID 35163229, 2022). "Mutations in SEC23B lead to congenital dyserythropoietic anemia type II (CDA-II)." (PMID 34169326, 2021). "Mutations in human SEC23B cause congenital dyserythropoietic anemia type II (CDAII), characterized by a specific defect in erythrocyte development while Sec23b deficient mice have a markedly different phenotype, exhibiting pancreatic disruption and disintegration." (PMID 23596517, 2013). "Finally, recent studies in patients with congenital dyserythropoietic anemia type II (CDAII) uncovered mutations in the SEC23B gene revealing its essential role in erythrocyte lineage development." (PMID 20442775, 2010). "Mutations in the SEC23B gene (Sec23 homolog B; MIM# 610512, 20p11.23) cause the vast majority of the congenital dyserythropoietic anemia Type II (CDA II MIM# %224100), an autosomal recessive disorder that represents the most common form of CDAs." (PMID 20941788, 2010). "In subsequent pregnancies 25–26, the diagnosis of SEC23B-related congenital dyserythropoietic anemia type II explained polyhydramnios and hydrops in both fetuses but not the cerebellar and skeletal anomalies." (PMID 41595457, 2025).
anemia (11 papers, 2011 to 2025). A reduction in the number of red blood cells, the amount of hemoglobin, and/or the volume of packed red blood cells. "In contrast to all the reported SEC23B-deficient mice so far, Sec23bki/ko mice did exhibit a mild to moderate anemia phenotype." (PMID 34954140, 2022). "While germline recessive loss-of-function mutations in SEC23B in humans cause a rare form of anaemia, heterozygous change-of-function mutations result in increased predisposition to cancer." (PMID 33753724, 2021). "The reduction of SEC23B presents an intriguing explanation for the macrocytic anemia in individual V-8, since biallelic variants in one of the SEC24 binding partners, SEC23B, cause congenital dyserythropoietic anemia type II (anemia, congenital dyserythropoietic, type II; CDAN2, OMIM 224100)." (PMID 40131364, 2025). "Despite the association of SEC23B with anaemia and cancer, the precise pathophysiology of these phenotypic outcomes remains unknown." (PMID 33753724, 2021). "For the remaining 17/19 cases of unexplained anaemia, no pathogenic mutations in ORCP genes were identified although one case (P13) was found to have mutations of uncertain significance in SEC23B, which may be partly responsible for her anaemia (Table SIV)." (PMID 27432187, 2016). "SEC23B-deficient mice pups are born with no obvious anemia and die shortly after birth, whereas SEC23A-deficient animals die during mid-embryogenesis with defects in neural tube closure and extraembryonic membrane formation." (PMID 37373084, 2023). "We previously reported that mice with near complete deficiency for SEC23B were born with no apparent anemia phenotype, but died shortly after birth, with degeneration of professional secretory tissues, in particular degeneration of the pancreas." (PMID 34954140, 2022). "We previously showed that in contrast to humans, mice with hematopoietic SEC23B deficiency do not exhibit anemia or other CDAII characteristics." (PMID 34818036, 2021). "We have previously demonstrated that in contrast to humans, mice with erythroid-specific SEC23B deficiency do not exhibit anemia or a defect in erythroid maturation." (PMID 34818036, 2021). "We did not observe any correlation between degree of anemia, type of mutation, and relative SEC23B mRNA reduction (data not shown)." (PMID 22208203, 2011). "One example of this is the Sec23b mutant mouse which does not recapitulate a type of anaemia termed congenital dyserythropoietic anaemia type II CDA-II, known to be caused by biallelic mutation of SEC23B in humans." (PMID 31164570, 2018). "Whereas mutations in the SEC23B gene are responsible for CDA II, mutations in SEC23A result in cranio-lenticulo-sutural dysplasia, a disease characterized by bone abnormalities, in absence of anemia." (PMID 37373084, 2023).
Cowden syndrome (4 papers, 2016 to 2024). "A previous study of the whole exome sequences in FNMTC revealed that SEC23B was a novel susceptibility gene in Cowden syndrome and identified a heterozygous missense SEC23B variant (c." (PMID 31595159, 2019). "SEC23B is implicated in endoplasmic reticulum to Golgi apparatus transport, and has also been recently associated with Cowden syndrome." (PMID 30871259, 2019). "No other non-hematologic abnormalities have been reported to result from SEC23B mutations, though a recent report suggested that germline heterozygous SEC23B variants are associated with Cowden syndrome and apparently sporadic thyroid cancer." (PMID 27297878, 2016). "Therefore, both SEC23A and SEC23B have vital functions in human beings, loss of which would cause serious diseases; particularly, lost SEC23B closely associated with Cowden syndrome, which has potentially cancer predisposing." (PMID 31595159, 2019). "As a novel susceptibility gene in Cowden syndrome, the SEC23B variant (c." (PMID 31595159, 2019). "In Cowden syndrome (OMIM: 616858), a missense mutation in Sec23B was identified in patients that inhibited binding to Sar1 and caused Sec23B aggregation, inducing a cancer-like phenotype in HEK293T cells." (PMID 38314136, 2024). "It is also interesting to highlight candidate genes involved in hereditary cancer (BRCA2, BLM, ERCC2, SMARCA4) or connected to inherited CRC, such as Cowden syndrome (SEC23B) and Peutz–Jeghers syndrome (STK11IP)." (PMID 30871259, 2019).
erythroleukemia (2 papers, 2020 to 2021). Acute erythroid leukemia characterised by the presence of at least 50% erythroid precursors and at least 20% myeloblasts in the bone marrow. "To determine whether SEC23A also functionally compensates for SEC23B deficiency in human erythroid cells, we first generated clonal human erythroleukemia K562 cell lines that are deficient in SEC23B using CRISPR-Cas9 genome editing." (PMID 34818036, 2021).
melanoma (2 papers, 2018 to 2019). A malignant, usually aggressive tumor composed of atypical, neoplastic melanocytes. "By searching for mutations of SEC23B in publicly available human cancer databases, we found a mutation in human melanoma that converts S186 of SEC23B to asparagine (ID#: COSM5391641)." (PMID 30596474, 2018). "Interestingly, a mutation at the SEC23B S186 site, a cancer-related mutation occurring in human melanoma, could abolish the interaction between SEC23B and FBXW5, resulting in an increase in autophagy and promoting the survival of cancer cells." (PMID 31595159, 2019).
thyroid cancer (2 papers, 2020 to 2022). "In a study of 96 CS and CS-like affected patients with thyroid cancer patients, germline heterozygous SEC23B variants were observed in three patients (3%)." (PMID 35163487, 2022). "Previous studies have reported that alteration of SEC23B is associated with the development of thyroid cancer, colorectal cancer, and prostate cancer." (PMID 35163487, 2022). "Among the 2N patients, we detected six genes (POLR3F, SEC23B, ZNF133, C16orf45, RRN3, and NTAN1) which were overexpressed after irradiation and were duplicated in the genome of ALL patients with the second independent cancer being either meningioma or thyroid carcinoma." (PMID 32577795, 2020).
bone marrow failure (1 paper, 2020). "This includes genes mutated in rare hematological syndromes (ADA, GP6, IL17RA, PRF1, and SEC23B), reported in prior MDS/AML or inherited bone marrow failure (IBMF) series (DNAH9, SH2B3, and NAPRT1), or novel loci where loss-of- function of the identified germline variants was demonstrated (DHX34)." (PMID 32098966, 2020).
chronic pancreatitis (1 paper, 2022). A chronic inflammatory process causing damage and fibrosis of the pancreatic parenchyma. "Therefore, ER stress caused by SEC23B deficiency may trigger chronic pancreatitis in Sec23bki/ko mice." (PMID 34954140, 2022).
colon cancer (1 paper, 2020). "To investigate the impact of SEC23B on tumor metastasis, we evaluated SEC23B expression in several colon cancer cell lines." (PMID 32123160, 2020). "Moreover, SEC23B expression was also found to be negatively correlated with tumor malignancy in both colon cancer and rectal cancer." (PMID 32123160, 2020).
Ewing sarcoma (1 paper, 2023). A small round cell tumor that lacks morphologic, immunohistochemical, and electron microscopic evidence of neuroectodermal differentiation. "VUS were also detected in NF1 in a patient without clinical symptoms of NF1, BRCA2 in a patient with nephroblastoma, SMARCA4 in a patient with Ewing sarcoma, and SEC23B, a candidate gene for Cowden, in a patient with multiple tumours and an additional pathogenic heterozygous RECQL4 variant." (PMID 37507557, 2023).
hemochromatosis (1 paper, 2021). A disorder of iron metabolism characterized by a triad of HEMOSIDEROSIS; LIVER CIRRHOSIS; and DIABETES MELLITUS. "In addition, we also identified variants from the hemochromatosis set of genes, two HFE variants and one in the SEC23 homolog B (SEC23B) gene, which was found to be associated with a different condition." (PMID 34349782, 2021).
hepatocellular carcinoma (1 paper, 2019). A malignant tumor that arises from hepatocytes. "Other previous studies showed that alteration of SEC23B was associated with the development of thyroid cancer 78, hepatocellular cancer 79, and prostate cancer." (PMID 31595159, 2019).
iron overload (1 paper, 2022). "We herein demonstrated, for the first time, a direct role of SEC23B loss-of-function variants as contributing cause of CDA II-related iron overload at hepatic level." (PMID 35163229, 2022). "Moreover, understanding the molecular mechanism that underlies SEC23B loss-of-function at hepatic level shed light on new therapeutic strategies of iron overload in CDA II." (PMID 35163229, 2022).
medullary thyroid carcinoma (1 paper, 2019). "In addition, reduced SEC23A expression increased sensitivity of medullary thyroid carcinoma to vandetanib treatment, all of which suggest that SEC23A could be a tumor suppressor gene, indicating opposing roles for SEC23A and SEC23B in cancer, although their role in cells is interchangeable in vivo." (PMID 31595159, 2019).
prostate carcinoma (1 paper, 2019). A carcinoma that arises from epithelial cells of the prostate gland. "However, knockdown of SEC23B expression mimicked the effect of miR-130a overexpression in prostate cancer cells." (PMID 31595159, 2019). "In addition, SEC23B is shown to be a target of miR-130a and the latter was downregulated in prostate cancer 80, whereas miR-130a overexpression in prostate cancer cells reduced tumor cell proliferation and invasion capacity but induced apoptosis." (PMID 31595159, 2019). "This study implies that SEC23B could be an oncogene in prostate cancer." (PMID 31595159, 2019).
Saul-Wilson syndrome (1 paper, 2023). "Some disorders have also been reclassified as CDG as the expansion of their pathophysiological mechanisms has included underlying glycosylation defects (e.g., Saul-Wilson syndrome [COG4], Cowden syndrome 7 [SEC23B], ALG5- and ALG9-CDG)." (PMID 37858231, 2023).
cancer (8 papers, 2018 to 2024). A tumor composed of atypical neoplastic, often pleomorphic cells that invade other tissues. "On average, the median age of cancer onset was significantly lower in patients harbouring a Sec23B mutation than those with wild type Sec23B (36 vs. 46 years old)." (PMID 38314136, 2024). "This demonstrates that Sec23B mutations have a role in sporadic cancer formation, suggesting a more important role for Sec23B in carcinoma than is currently understood." (PMID 38314136, 2024). "Mutations in Sec23B have also been linked to oncogenic phenotypes and are found in cancer (discussed in Section 4.3)." (PMID 38314136, 2024). "In contrast, we recently identified SEC23B as a candidate cancer-predisposition gene associated with CS (MIM 158350) and apparently sporadic thyroid cancer." (PMID 33753724, 2021). "Interestingly, SEC23A and SEC23B are associated with autophagy, which is involved in cancer development and progression." (PMID 31595159, 2019). "SEC23 protein has two isoforms (SEC23A and SEC23B) and their aberrant expression and mutations were reported to cause human diseases and oncogenesis, whereas SEC23A and SEC23B may have the opposite activity in human cancer, for a reason that remains unclear." (PMID 31595159, 2019). "Overall, these observations suggest that SEC23B, irrespective of mutation status, has unexplored roles in the cellular stress response pathway, with implications relevant to cancer and beyond that, CDAII and normal cell biology." (PMID 33753724, 2021). "Based on these few studies, we concluded that SEC23B expression is frequently upregulated in these types of human cancer and functions as an oncogene or possesses oncogenic activity in these cancers." (PMID 31595159, 2019). "Additionally, 75% of sporadic cancers in the database showed overexpression of Sec23B transcripts, with 10% showing a high level of transcript amplification, suggesting that the mutations are likely to be deleterious." (PMID 38314136, 2024). "The fact that SEC23B can coexist with classic cancer-related proteins within nucleolar aggresomes raised the question as to whether SEC23B protein directly interacts with such pertinent proteins." (PMID 33753724, 2021). "However, additional research is needed to understand the precise function and role of SEC23A and SEC23B in human disease and cancer development." (PMID 31595159, 2019). "This section will discuss the role of SEC23 in human cancer development and progression, although previous studies revealed that SEC23A and SEC23B might have been opposing roles in cancer." (PMID 31595159, 2019). "Indeed, we have recently identified SEC23B and USF3 as candidate cancer susceptibility genes in PTEN-wildtype CS, and TTN in PTEN-wildtype BRRS." (PMID 29684080, 2018). "Indeed, during cancer development and progression, a great number of proteins are produced and transported in cancer cells, and SEC23B may play an important role in this process." (PMID 31595159, 2019). "Furthermore, another study demonstrated that SEC23B contributed to cancer predisposition through the ribosome biogenesis pathway, independent of SEC23B-mediated COPII functions." (PMID 31595159, 2019). "However, more studies are needed to clarify the role of SEC23B in human cancer." (PMID 31595159, 2019). "In vivo, the functions of SEC23A and SEC23B have been found to be interchangeable in COPII, whereas SEC23A and SEC23B may have the opposite activity in human cancer for unknown reasons." (PMID 37046730, 2023). "Recently, we reported that mutant SEC23B has non-canonical COPII-independent function, particularly within the ER stress and ribosome biogenesis pathways, and that may contribute to the pathobiology of cancer predisposition." (PMID 33753724, 2021).
tumor (8 papers, 2018 to 2024). "The number of lung metastases was quantified, and mice injected with mutant SEC23B cells showed more metastases than those injected with WT SEC23B, suggesting that SEC23B mutations promote tumor metastasis in vivo." (PMID 32123160, 2020). "Our study highlights the significance of SEC23B in tumor metastasis, and provides a potential biomarker for CRC progression." (PMID 32123160, 2020). "To assess the function of SEC23B on tumor progression, we established a SEC23B-knockout (KO) cell line using CRISPR technique, and validated the down-regulation of SEC23B with sequencing and immunoblotting." (PMID 32123160, 2020). "To obtain insights into the impact of SEC23B mutations clinically, we further examined the significance of SEC23B on CRC progression, and found that patients with lower level of SEC23B tended to have shorter survival, indicating that low level of SEC23B accelerate tumor progression." (PMID 32123160, 2020). "However, the impact of SEC23B on tumor metastasis is largely unknown." (PMID 32123160, 2020). "The proliferation rate of SEC23B knockout cell was not significantly changed in MTT assay, suggesting that tumor metastases in patient with C649T mutation were unlikely due to excessive primary tumor growth." (PMID 32123160, 2020).
autosomal recessive disease (2 papers, 2021 to 2022). Autosomal recessive form of disease. "CDAII is an autosomal recessive disease resulting from loss-of-function mutations in SEC23B." (PMID 34818036, 2021).
SEC23B also shares sentences with these, for which no sentence is quoted: congenital dyserythropoietic anemia (3 papers); breast tumor (2); Majeed syndrome (2); angiosarcoma (1); breast carcinoma (1); chylomicron retention disease (1); colorectal cancer (1); craniolenticulosutural dysplasia (1); craniorachischisis (1); Diamond-Blackfan anemia (1); genetic diseases (1); Hepatomegaly (1); hereditary cancer (1); hereditary spherocytosis (1); hydrops (1); hypoglycaemia (1); infection (1); macrocytic anemia (1); meningioma (1); myeloid malignancies (1); Nephroblastoma (1); Obesity (1); osteogenesis imperfecta (1); pancreatic insufficiency (1); pancreatitis (1); periodontitis (1); rectal cancer (1); Splenomegaly (1).